TREM1 (triggering receptor expressed on myeloid cells 1)
Diseases named in the same sentence as TREM1 in open-access papers (continued):
Sharing a sentence is not in itself a finding about the gene and the disease.
Arthritis (9 papers, 2013 to 2025). Inflammation of a joint. "Triggering receptor expressed on myeloid cells 1 (TREM1) is highly expressed in the synovial tissue of arthritis mice and is closely associated with aberrant mitophagy." (PMID 40821693, 2025). "In experimental and clinical arthritis, TREM-1 is well known to mediate the release of proinflammatory cytokines and chemokines, including CSF-1, that are all implicated in RA disease pathogenesis." (PMID 36012120, 2022). "In experimental arthritis, therapeutic inhibition of TREM-1 ameliorates disease and, importantly, can blunt excessive inflammation without affecting pathogen clearance." (PMID 36012120, 2022). "Increase in TREM-1 expression in peripheral blood neutrophil has been well documented for most arthritis types." (PMID 27792788, 2016). "Additionally, they found that arthritis patients exhibited significantly increased protein expression and mRNA levels of TREM1 in tendon cells compared to the non-arthritis group." (PMID 40011963, 2025). "Thus, when given before arthritis begins, the 140 nm-sized TREM-1 inhibitory LPC formulations may effectively prevent CIA, most likely by means of inhibiting systemic inflammatory response." (PMID 36012120, 2022). "In this study, we showed that in experimental arthritis, inhibiting TREM-2 ameliorated arthritis and significantly reduced cartilage and joint damage, similarly to what happens when inhibiting TREM-1." (PMID 36012120, 2022). "TREM-1 expression of CD16+ neutrophils was significantly greater in Group-1 patients and this can be attributed to the severity of arthritis." (PMID 27792788, 2016).
asthma (9 papers, 2014 to 2025). "A different study demonstrated that atorvastatin inhibited airway wall remodeling associated with asthma through downregulating the expression of TREM-1." (PMID 40319222, 2025). "Interestingly, associations between asthma and TREM1 pathway signalling activity have been reported by several groups, and relative suppression of the TREM1 signalling pathway has been reported in eosinophilic nasal polyposis." (PMID 37334358, 2023). "A recent study identified an association between TREM1 in a blood signature and asthma control, suggesting that this gene may be a potential marker of disease activity, it is unknown how TREM1 expression, asthma control and asthma exacerbations are related to each other." (PMID 29486764, 2018). "Whether elevated titres of autoantibodies to TREM1 in severe eosinophilic asthma, as identified in this research, are an epiphenomenon or whether these autoantibodies have a functional role in asthma pathology will require more research." (PMID 37334358, 2023). "Furthermore, we found that the expression of some molecules such as CD14, TLR5, TLR6, TLR8, TREM-1, but also IRAK-1 and IRAK-2 genes was significantly negatively associated with total serum IgE, atopic sensitization, or asthma." (PMID 24603716, 2014).
endothelial dysfunction (9 papers, 2019 to 2025). In vascular diseases, endothelial dysfunction is a systemic pathological state of the endothelium (the inner lining of blood vessels) and can be broadly defined as an imbalance between vasodilating and vasoconstricting substances produced by (or acting on) the endothelium. "Further analysis is needed to validate these findings and reveal the underlying mechanism of TREM-1 in the pathophysiology of endothelial dysfunction." (PMID 41451290, 2025). "TREM-1 may, therefore, constitute a new therapeutic target to prevent NETosis and associated endothelial dysfunction." (PMID 33420354, 2021). "Our study provides new insights into the function of TREM-1 and its ability to predict endothelial dysfunction in individuals with type 2 diabetes." (PMID 41451290, 2025). "Profile 1 patients were characterized by higher vasopressor dose requirement at H24, which suggests that TREM-1 engagement potentiated post-CPB endothelial dysfunction and related impaired vasomotor tone." (PMID 37522081, 2023). "However, there have been few investigations into the relationship between TREM-1 and endothelial dysfunction in patients with type 2 diabetes." (PMID 41451290, 2025). "As such, the design of endothelium-specific TREM-1 inhibitors may prove interesting in preventing endothelial dysfunction while preserving myeloid cells functionality." (PMID 31632399, 2019). "Therefore, the potential mechanisms of TREM1 in endothelial dysfunction may involve the synthesis of inflammation amplification and subsequent oxidative stress imbalance." (PMID 41451290, 2025). "Furthermore, abnormalities in TM and TREM-1 expression in some immune cells may indicate a failure of anti-coagulant and anti-inflammatory responses, contributing to microvascular thrombosis, impaired tissue perfusion, and sustained organ failure—hallmarks of endothelial dysfunction in septic shock." (PMID 41425588, 2025). "Moreover, TREM-1 activation was shown to result in a persistent release of cytokines and chemokines (tumour necrosis factor alfa [TNF-α], IL-1β, IL-8, and monocyte chemotactic protein [MCP]-1), and is directly related to endothelial dysfunction and platelet activation." (PMID 34195785, 2021).
lung injury (9 papers, 2016 to 2024). "The triggering receptor expressed on myeloid cells-1 (TREM-1) is a pro-inflammatory immune receptor potentiating acute lung injury (ALI)." (PMID 36594089, 2023). "The triggering receptor expressed on myeloid cells 1 (TREM-1) activation through mTOR-mediated signaling promotes Drp1-dependent mitochondrial fission, mitophagy, and necroptosis of alveolar macrophages during acute lung injury." (PMID 38576612, 2024). "A previous study also suggested that the balance of TREM-1 and TREM-2 regulated the progression of acute lung injury." (PMID 34176389, 2021). "Blocking TREM-1 with LR12, a TREM-1 antagonist peptide, has shown a significant protective effect on LPS-induced acute lung injury via inhibiting the activation of the NLRP3 inflammasome." (PMID 32984356, 2020). "Because TREM-1 is reported to amplify the inflammatory response initiated by TLR engagement, we further investigated whether TLR4 signaling was inhibited by MH in acute liver injury." (PMID 31616301, 2019).
prostate carcinoma (9 papers, 2015 to 2025). A carcinoma that arises from epithelial cells of the prostate gland. "In thyroid and prostate cancer cells TREM1 expression is regulated by epigenetic modifications, specifically hypomethylation of CpG site Cδ06196379 in the TREM1 promoter region and has significant prognostic value in thyroid tumors." (PMID 40677705, 2025). "In prostate cancer (PCa), upregulation of the TREM-1 mediated the activation of androgen receptor signaling in macrophages to promote PCa-derived cancer cell progression." (PMID 39744496, 2025). "Altogether, among the five cell lines we studied (two breast and three prostate cancers), four resistant clones have elevated levels of TREM1 or CCL2." (PMID 33664852, 2021). "TREM1/CCL2 activation, in addition to restored ASS1 expression, as a key pathway involved in full ADI-resistance in breast and prostate cancer models." (PMID 34884583, 2021). "In the present study, we found significantly elevated expression of TREM1 in independently selected ADI resistant clones from both breast and prostate cancer cell lines, suggesting a functional role of TREM1 in drug resistance." (PMID 33664852, 2021). "Furthermore, oxidative phosphorylation, p70S6K, unfolded response, TREM1, NFκB, ERK5, IL8, BAG2, Integrin, and VEGF signaling were identified (z score 5.574 to −4.811) as top canonical pathways for ARLow/mCRPC/NEPC prostate cancer." (PMID 37476073, 2023).
Shock (9 papers, 2011 to 2025). The state in which profound and widespread reduction of effective tissue perfusion leads first to reversible, and then if prolonged, to irreversible cellular injury. "Soluble isoform of TREM-1 has been shown to attenuate the inflammatory response and improve survival in animal models of septic shock by inhibiting the TREM-1 receptor-mediated amplification of the inflammatory response in neutrophils and monocytes." (PMID 25927603, 2015). "The functional significance of TREM-1 was discovered when it was observed that the blockade of TREM-1 signaling protects mice from the lethal effects of lipopolysaccharide-induced septic shock." (PMID 24778096, 2014). "Inhibition of TREM1 reduced inflammatory symptoms and improved survival during mesenteric ischemia-reperfusion injury and hemorrhagic shock." (PMID 24358193, 2013). "A ligand-independent peptide inhibitor, GF9, targeting the TREM-1 transmembrane domain and preventing the TREM-1/DAP12 interaction, has shown therapeutic efficacy in models of septic shock." (PMID 32456204, 2020).
bacterial sepsis (8 papers, 2007 to 2024). "Among these, we found up-regulated genes encoding for inflammation and phagocytosis associated proteins (e.g., Apoe, Lgals3, Trem1, and C3), indicating a prolonged transcriptional activation of microglia for at least 20 days following bacterial sepsis." (PMID 37235660, 2023). "We hypothesized that Trem-1 expression on neutrophils and/or monocytes associated with endotoxin tolerance in severe bacterial sepsis." (PMID 23414215, 2013). "Triggering receptor expressed on myeloid cells-1 (TREM-1) is a recently discovered member of the immunoglobulin superfamily of receptors that is specifically expressed on the surfaces of neutrophils and monocytes and upregulated in bacterial sepsis." (PMID 27239102, 2016). "The TREM-1 pathway on neutrophils might play a role in producing an adequate inflammatory and bactericidal response in bacterial sepsis." (PMID 23414215, 2013). "TREM-1 is a DAP12-associated receptor expressed on neutrophils and monocytes that plays a key role in the protecting the host against fungal allergens, parasites as well as in bacterial sepsis, collagen-induced arthritis, and inflammation-associated tumor development." (PMID 30555461, 2018).
chronic obstructive pulmonary disease (8 papers, 2008 to 2025). A chronic and progressive lung disorder characterized by the loss of elasticity of the bronchial tree and the air sacs, destruction of the air sacs wall, thickening of the bronchial wall, and mucous accumulation in the bronchial tree. "TREM1 promoted inflammation in patients with chronic obstructive pulmonary disease by activating caspase-1-induced pyroptosis." (PMID 38333413, 2024). "Additionally, and in strict contrast to patients who suffer from Chronic Obstructive Pulmonary Disease (COPD), CF monocytes challenged ex vivo with LPS neither up-regulated membrane-anchored TREM-1 nor sTREM-1." (PMID 18628981, 2008).
colorectal cancer (8 papers, 2017 to 2022). A primary or metastatic malignant neoplasm that affects the colon or rectum. "Mounting evidence indicated that the overexpression of TREM1 is associated with the development of several types of cancer, such as colorectal carcinoma and hepatocellular tumor." (PMID 32296463, 2020). "Here, we demonstrate that genetic deficiency in Trem1 protects from colorectal cancer." (PMID 29093489, 2017). "TREM-1 inhibition by LP17 have been studied in vivo, in mouse models of IBD-associated colorectal carcinoma." (PMID 35875168, 2022). "Canonical pathway analysis has shown effects on the TH2 pathway, IL8 signaling, TREM1 signaling, colorectal cancer metastasis signaling, NFAT in regulation of the immune response, and IL-17F in allergic inflammatory airway diseases." (PMID 30622539, 2018).
liver cancer (8 papers, 2016 to 2025). An epithelial or non-epithelial malignant neoplasm that arises from the liver. "In hypoxic microenvironment, the TREM-1-expressing M2-like TAMs recruit CCR6-containing Tregs near liver cancer cells by secreting CCL20, which is the principal cause of resistance to anti-PD-L1 immunotherapy in liver cancer." (PMID 35672862, 2022). "In the liver, TREM1 expression has been implicated in multiple hepatic diseases including liver cancer, fatty liver disease, alcoholic liver disease and other drivers of liver injury and fibrosis." (PMID 31260499, 2019). "Triggering receptor expressed on myeloid cells (TREM)-1 is a key mediator of innate immunity previously associated with the severity of inflammatory disorders, and more recently, the inferior survival of lung and liver cancer patients." (PMID 34956864, 2021). "To further validate our findings and explore the role of TREM1 in liver cancer at the cellular level, we assessed TREM1 expression in human HCC cell lines (Huh7, HepG2, Hep3b) and one primary HCC patient (P1)." (PMID 40677705, 2025). "To address this gap, we investigated the role of TREM1 in two well-established liver cancer cell lines Huh7 and HepG2 using control and CRISPR-Cas9 TREM1 KO cells." (PMID 40677705, 2025). "Evidence has revealed that TREM1 inhibitors can sensitize tumor cells to anti-PD-L1 immunotherapy for liver cancer." (PMID 38370418, 2024). "In order to evaluate the expression of TREM1 in liver cancer tissues, a tissue microarray was used to detect TREM1 expression." (PMID 38914803, 2024). "A role for TREM-1 signaling in tumor formation is supported by studies in TREM1 knockout mice that model inflammation-driven liver cancer and CRC." (PMID 34956864, 2021). "Our data indicates that TREM1 is expressed in liver cancer cells and tissues." (PMID 40677705, 2025). "Additionally, we employed cell line-derived xenograft (CDX) models and bulk RNA-sequencing to determine the role of TREM1 in CD133+EpCAM+ LCSLCs in liver cancer." (PMID 40677705, 2025). "Interestingly, preliminary flow cytometry analysis demonstrated that TREM1 silencing significantly reduced the proportion of CD133+EpCAM+ liver cancer stem-like cells (LCSLCs)." (PMID 40677705, 2025). "The results revealed a significant upregulation of TREM1 in liver cancer tissue." (PMID 38914803, 2024). "In co-culture experiments, TREM-1 signaling was reported to induce migration of liver cancer cells, which could be abrogated by incubation with a TREM-1-blocking peptide." (PMID 34956864, 2021). "This also validates the results we obtained from using Huh7 CRISPR-Cas9 TREM1 KO cells and highlights the potential of VJDT as a therapeutic agent in targeting liver cancer stem-like cells." (PMID 40677705, 2025).
melanoma (8 papers, 2021 to 2025). A malignant, usually aggressive tumor composed of atypical, neoplastic melanocytes. "In cancer models, Trem-1 deficiency led to reduced tumor growth (melanoma, fibrosarcoma), less immunosuppressive activity of MDSCs and higher expression of PD-1 on CD8+T cells, pointing to a role in shaping the tumor immune microenvironment." (PMID 41226426, 2025). "High TREM1 expression is associated with poor prognosis in human cancers, and TREM1 inhibition reduces tumor burden in melanoma patient–derived xenografts." (PMID 37651197, 2023). "We demonstrated that genetic or pharmacological TREM1 silencing significantly delayed tumor growth in murine melanoma (B16F10) and fibrosarcoma (MCA205) models." (PMID 37651197, 2023). "Our scRNA-Seq analysis of CD45+ TICs in the melanoma model demonstrated a substantial alteration of the tumor immune landscape under Trem1 silencing." (PMID 37651197, 2023). "Additionally, a recent study showed that TREM1 plays a role in the inflamed tumor microenvironment, and its inhibition enhances the antitumorigenic effect of anti–PD-1 treatment in murine melanoma, representing an attractive therapeutic target for cancer." (PMID 40881686, 2025). "Previous studies showed that tumor growth in murine melanoma and fibrosarcoma models could be delayed by inhibiting TREM1 gene expression." (PMID 41413734, 2025). "Furthermore, to comprehensively characterize the changes within the TME during TREM1 deficiency and anti-PD-1 ICB, we performed scRNA-Seq analysis of the CD45+ TICs in melanoma-bearing Trem1+/+ mice receiving the various treatments." (PMID 37651197, 2023). "To analyze the impact of TREM1 on tumor growth and immune responses, we used 2 transplantable syngeneic mouse tumor models, the B16F10 melanoma and MCA 205 fibrosarcoma cell lines, known to be associated with a microenvironment infiltrated with myeloid and lymphoid cells." (PMID 37651197, 2023). "A previous study on melanoma found that the increased ratio of TREM-1 to TREM-2 may promote the pro-inflammatory and pro-tumor state of the tumor microenvironment." (PMID 34122331, 2021). "This is exceptionally fortuitous as our prior studies demonstrated that TREM1 inhibition remodels the TME to a more immunopermissive state and augments anti-PD-1 treatment to overcome its resistance in melanoma." (PMID 40677705, 2025). "Triggering receptor expressed on myeloid cells 1 (TREM1) was found to suppress the antitumor immune response, and its inhibition significantly delays melanoma growth." (PMID 40312750, 2025). "Further, by utilizing the melanoma PDXs, we demonstrated that VJDT treatment pharmacologically inhibits TREM1 and curbs tumor growth." (PMID 37651197, 2023). "Marked downregulation of expression of TREM1 and known TREM1 target genes (NFKB1, CCL20, IL6, and CXCL8) was determined in melanoma PDX models treated with VJDT." (PMID 37651197, 2023). "We found that the growth of mouse melanoma (B16F10) and fibrosarcoma (MCA205) tumors was delayed in Trem1–/– mice or in Trem1+/+ mice treated with VJDT." (PMID 37651197, 2023). "In this study, we analyzed the impact of TREM1 in tumor progression utilizing a combination of Trem1–/– mice, silencing of TREM1 in human cancer cells, and pharmacological inhibition of TREM1 via the small molecule inhibitor VJDT in several mouse tumors and a melanoma PDX model." (PMID 37651197, 2023). "In mouse melanoma (B16F10) and fibrosarcoma (MCA205) models, genetic or pharmacological inhibition of TREM1 expression could reduce the infiltration of myeloid derived suppressor cells (MDSCs), while increasing the proportion of cytotoxic CD8+T to inhibit tumor growth." (PMID 39744496, 2025).
non-small cell lung carcinoma (8 papers, 2009 to 2024). A group of at least three distinct histological types of lung cancer, including non-small cell squamous cell carcinoma, adenocarcinoma, and large cell carcinoma. "TREM-1 is also reported to be expressed in tumor-associated macrophages (TAM) in non-small cell lung cancer in previous studies." (PMID 29844416, 2018). "In summary this study shows that human non-small cell lung cancers have a high expression of TREM-1 in tumor associated macrophages." (PMID 24842612, 2014). "High expression of TREM1 in tumor-associated macrophages was reported to correlate with cancer recurrence and poor survival in patients with non-small cell lung cancer." (PMID 19536297, 2009). "Moreover, PGE2 promotes the expression of TREM-1 in macrophages induced by LPS or human non-small-cell lung cancer-associated macrophages." (PMID 31287012, 2019). "Blockade of TREM-1 by the delivery of the inhibitor peptide GF9 significantly abolished tumor progression in human xenograft models of non-small cell lung cancer." (PMID 35875168, 2022). "In this study we demonstrate that tumor tissue from patients with non-small cell lung cancer show an increased expression of TREM-1 and PGE2." (PMID 24842612, 2014). "We conducted this study to determine cell specific expression of TREM-1 in human non-small cell lung cancer (NSCLC) tissue and to define the mechanism by which tumor cells induce expression of TREM-1." (PMID 24842612, 2014).